INS (insulin)
Diseases named in the same sentence as INS in open-access papers (continued):
Sharing a sentence is not in itself a finding about the gene and the disease.
diabetes (continued). "Our aim in this study was to examine the effects of silibinin on insulin secretion, anxiety‐like behaviors, and learning in a streptozotocin (STZ)‐induced rat diabetes model." (PMID 38726421, 2024). "This difference was driven largely by the subgroup of patients with diabetes requiring insulin, of which four of the five (80.0%) patients were admitted to a high-dependency unit (HDU) for a diabetes-related complication." (PMID 38392055, 2024). "Data pertaining to the mortality rate of preexisting diabetes, incidence of light-induced diabetes and IGT, and alterations in insulin secretion were collected and analyzed." (PMID 39950097, 2024). "Patients with HNF1A-diabetes exhibit reduced insulin secretory capacity, while those with GCK-diabetes display defective glucose sensitivity but retain insulin secretory capacity." (PMID 39902162, 2024). "The review covers the detection of several key diabetes biomarkers, such as glucose, glycated hemoglobin (HbA1c), glycated human serum albumin (GHSA), insulin, and novel biomarkers." (PMID 39091901, 2024). "In the first phases of this process, an increase in insulin secretion (hyperinsulinemia) compensates for the peripheral resistance, but when insulin response is no longer adequate to the demands, a hyperglycemic state is established, which may progressively evolve to type 2 diabetes mellitus." (PMID 38337711, 2024). "T2DM and type 1 diabetes mellitus (T1DM) can be distinguished as follows: T1DM is characterized by the immune system destroying pancreatic beta cells indefinitely; consequently, insulin production is very low or null." (PMID 38397953, 2024). "The dysfunction of miRNAs significantly contributes to the onset and progression of type 2 diabetes mellitus (T2DM), playing crucial roles in insulin secretion, glucose homeostasis, and adipocyte differentiation." (PMID 39000190, 2024). "Although insulin levels were expected to be low in all groups subjected to STZ application (Diabetes, S 100, S 200), a significant decrease was observed only in the diabetes group." (PMID 38726421, 2024). "Furthermore, those on insulin in the WG medication group are likely to have had T2D for a longer duration, indicating a more advanced stage of diabetes that could exacerbate corneal nerve damage directly or through comorbidities such as obesity, abnormal lipid profiles, and renal impairment." (PMID 39439079, 2024). "In diabetes, FGF21 is commonly considered to be a protective factor due to its insulin-sensitizing and anti-inflammatory effects." (PMID 38540101, 2024). "Biguanides, DPP-4 inhibitors, GLP-1 agonists, Insulin, and SGLT-2 inhibitors are the most common diabetes medications." (PMID 39759947, 2024). "Diabetes mellitus (DM), mainly represented by type 2 diabetes, accounting for more than 90% of all cases, is a chronic metabolic disorder characterized by persistent hyperglycemia, resulting from decreased insulin secretion, insulin resistance, or both." (PMID 39000680, 2024). "Additionally, a grandmother in her 50s has recently received a diagnosis of diabetes mellitus (DM) managed with insulin, and rheumatoid arthritis, and her screening genetic testing was positive for IPEX syndrome as a carrier." (PMID 39372653, 2024). "As seen in patients with type 1 DM in the Diabetes Control and Complications Trial (DCCT), insulin therapy reduced CVD events by improving glycemic control." (PMID 38366387, 2024). "Management of double diabetes in PWS necessitates a multidisciplinary approach, encompassing interventions such as weight management, insulin sensitizers, behavioral therapy, and counseling." (PMID 39135667, 2024). "Diabetes mellitus (DM) is a group of metabolic illnesses characterized by elevated levels of glucose in the bloodstream as a result of abnormalities in the generation or function of insulin." (PMID 39031306, 2024).
diabetes (continued). "Another potential mechanism for the increased BMD in diabetic patients relates to elevated levels of insulin and insulin-like growth factor-1 (IGF-1), particularly during the early stages of diabetes or in cases characterized by insulin resistance." (PMID 39741509, 2024). "Normally, insulin promotes NO production via the PI3K-Akt-eNOS pathway, but in type 2 diabetes mellitus, this pathway is impaired, reducing NO availability and leading to vasoconstriction." (PMID 39728298, 2024). "This responsibility falls to the managing physicians, but the diabetes inpatient team (DIT) plays a crucial role in identifying high-risk patients and assisting with complex cases, particularly those involving multiple treatments or insulin regime adjustment that might be indicated." (PMID 38387535, 2024). "The primary subtypes of DM are type 1 diabetes mellitus (T1DM) and type 2 diabetes mellitus (T2DM), typically arising from impaired insulin secretion (T1DM) and/or function (T2DM)." (PMID 39233978, 2024). "In diabetes, GSK-3 is an important target of insulin signaling, and its phosphorylation at specific residues leads to the inhibition of GSK-3 activity." (PMID 39655056, 2024). "Type 2 diabetes mellitus (T2DM) is a metabolic disorder distinguished by impairments in either insulin secretion, insulin action, or both." (PMID 38903536, 2024). "Diabetes drugs (GLP1 agonists) mimic GLP1 action, stimulating insulin production after glucose increase due to feeding." (PMID 39062927, 2024). "According to nominal p-values for interaction, we found better preservation of eGFR over time with dapagliflozin vs comparators in patients with longer diabetes duration, below-median baseline eGFR, CKD, UACR>30 mg/g, microangiopathy, or using insulin." (PMID 38328413, 2024). "SCD1 is a key regulator in lipid metabolism; high expression of SCD1 protein correlates with obesity, diabetes, and atherosclerosis and inactivation of SCD1 supports an HFD-resistant phenotype, reduced fat accumulation and insulin sensitivity." (PMID 38725872, 2024). "Upon induction of diabetes with STZ, the islets showed decreased insulin staining and less ins + cells as compared the control group (control, upper most panel; STZ, second panel from top)." (PMID 38698488, 2024). "In individuals with diabetes, depression heightens stress, leading to HPA axis hyperactivation, elevated cortisol levels, and reduced insulin sensitivity." (PMID 38916735, 2024). "Type 1 diabetes mellitus, commonly known as T1DM, is an autoimmune disorder in which the immune system targets and eliminates the beta cells in the pancreas that produce insulin." (PMID 39335472, 2024). "The role of GLP-1R in type 2 diabetes mellitus (T2DM) is highlighted, emphasizing its pivotal contribution to glucose homeostasis, promoting β-cell proliferation, and facilitating insulin release." (PMID 38801466, 2024). "Rats with diabetes had lower amounts of glycogen, I.R., and GLUT4 insulin signaling proteins and less glucose and insulin tolerance." (PMID 39619995, 2024). "ML selected age, use of insulin, duration of diabetes, and circulating tyrosine as the most important markers for DKD and DR detection in the SEED population with diabetes." (PMID 38546730, 2024). "The Diabetes Control and Complication Trial (DCCT) highlighted the critical role of intensive insulin therapy (IIT) in reducing both microvascular and macrovascular complications among people with type 1 diabetes mellitus (T1DM)." (PMID 39065641, 2024). "Diabetes mellitus (DM), commonly referred to as diabetes, is a chronic metabolic disorder characterized by persistent hyperglycemia resulting from defects in insulin secretion, insulin action, or both." (PMID 39664090, 2024). "As life expectancy increases among patients with type 2 diabetes mellitus (T2DM), they too will require insulin due to progressive β-cell failure." (PMID 39734941, 2024).
diabetes (continued). "The rats were divided into the following three groups: (i) control, (ii) streptozotocin (STZ)-induced diabetes model (T1DM model), and (ii) STZ-induced diabetes model treated with insulin treatment (T1DM–insulin model)." (PMID 39000424, 2024). "When examining the cohort as a whole, we found a positive relationship between SII and the markers of diabetes (i.e., FBG, HbA1c, insulin)." (PMID 38541168, 2024). "Differently from type 1 (insulin-dependent) diabetes, which occurs when there is deficient insulin production by the pancreas, type 2 (non-insulin-dependent) diabetes results from reduced insulin production, insulin resistance, or ineffective insulin use, representing 90% of people with diabetes." (PMID 38397470, 2024). "The pathophysiology of diabetes mellitus (DM) is attributed to a state of continued high blood glucose levels arising from inadequate amounts of insulin produced by the body or due to the inability of insulin to act on cells, a process also known as insulin resistance." (PMID 39692821, 2024). "Analyzing plasma samples from 380 men and 375 women for a predefined set of 184 proteins, the study revealed proteins related to insulin dynamics, such as IGFBP2 and TIMP4, emphasizing the gender specificity in diabetes pathogenesis." (PMID 39371930, 2024). "This study evaluated the effect of oral betaine on whole body insulin resistance and on hepatic insulin signaling in a high fat dietary model of insulin resistance in C57BL 6J mice, the standard strain of mice used for diabetes research." (PMID 39119463, 2024). "Inhibiting these enzymes improves insulin signaling and sensitivity (PTP-1B) and insulin secretion (DPP-4), which improves glycemic control in diabetes." (PMID 38675719, 2024). "In the current investigation, rats with diabetes induced by an HFD and STZ exhibited a notable rise in blood glucose levels and a substantial reduction in serum insulin concentrations." (PMID 39539448, 2024). "Insulin resistance is a crucial factor in the development of type 2 diabetes mellitus (T2DM), and long non-coding RNAs (lncRNAs) play significant roles in regulating insulin signaling and lipid metabolism." (PMID 39595541, 2024). "Those with average insulin OOPC per 30‐day supply >$35 or $0 were more likely to have an insulin refill lapse versus OOPC of >$0 to $20, with odds ratios ranging 1.18 (95% CI 1.13–1.22) to 1.74 (95% CI 1.66–1.83) depending on OOPC group and diabetes type." (PMID 36992575, 2024). "Diastolic dysfunction has been associated with non-cardiac drivers, such as hypertension, diabetes and obesity, and we have reported that the line of global Alms1 KO mice used in this study is, like other global KO models described previously, obese and insulin resistant." (PMID 38756069, 2024). "This study also reports on the protective role of insulin against amputations, underscoring the need to increase insulin administration in PLWD, to prevent diabetes-related complications." (PMID 38439010, 2024). "Diabetic patients with uncontrolled glycemic levels were transferred to insulin therapy or alternatively to dual therapy (Insulin + oral anti-diabetic agents), in accordance with the recommendations of the Malaysian CPG for type 2 diabetes mellitus (T2DM)." (PMID 38476498, 2024). "Type 2 diabetes mellitus (T2DM) is a chronic metabolic disorder characterized by hyperglycemia, insulin resistance, and decreased insulin secretion." (PMID 39723311, 2024). "A prior investigation has validated the participation of VGLUT2 in the transportation of glutamate during the insulin secretion process in pancreatic cells, implicating VGLUT2 in β cell apoptosis and, consequently, the onset of diabetes." (PMID 38370359, 2024). "The therapeutic properties of C. sativus in rats with diabetes induced by alloxan resulted in a decrease in FBG and HbA1c levels, as well as an increase in blood insulin levels." (PMID 38419885, 2024).
diabetes (continued). "In diabetes, TRPA1 regulates insulin secretion and sensitivity, indicating its therapeutic potential." (PMID 39273183, 2024). "The data presented indicate that liraglutide improves lipoatrophic diabetes in SKO mice, with both improvements to insulin sensitivity and enhanced glucose regulated insulin release." (PMID 38745956, 2024). "The insulin–heart axis plays a pivotal role in the pathophysiology of cardiovascular disease (CVD) in insulin-resistant states, including type 2 diabetes mellitus." (PMID 39337658, 2024). "Autoantibodies against pancreatic islet cells (ICA), IA-2, insulin, and GAD are highly specific in autoimmune diabetes and are characteristic of the first stage of T1DM and predictive of future diabetes onset." (PMID 39014283, 2024). "For the included 7601 adults aged 18–65, the age, gender, race, education, BMI, PA, glucose, insulin, HbA1c, HOMA-IR, and blood Ln-Pb were statistically different between diabetes and non-diabetes participants (p < 0.05)." (PMID 39853009, 2024). "OD gerbils demonstrated impaired adipose tissue function, increased ectopic fat deposition, and reduced insulin sensitivity compared to NOD gerbils, emphasizing the central role of adipose tissue function in the development of diabetes." (PMID 39474247, 2024). "In addition, the growing integration of advanced diabetes technologies, and artificial intelligence (AI), into the management of T1D presents considerable potential for improving glycemic control through decision support systems that optimize automated insulin therapy." (PMID 39519579, 2024). "In diabetes mellitus (DM), chronic hyperglycemia, oxidative stress, nerve alterations, and disturbance in insulin function may be fundamental aspects in the progression of changes in the ocular surface (OS) and impairment of the lacrimal gland (LG)." (PMID 38821986, 2024). "Reducing hyperglycemia with insulin, SGLT2 inhibitors, or a ketogenic diet for about three weeks can partially restore β-cell mass and aid in diabetes recovery, indicating that extreme glucotoxicity hinders regeneration." (PMID 39057094, 2024). "The development of diabetes can be influenced by environmental factors through the modulation of DNA methylation, which promotes the initiation of inflammatory responses and interferes with insulin secretion, and these effects may even be inherited by offspring." (PMID 40302954, 2024). "Type 2 Diabetes Mellitus (T2DM) is characterized by insufficient insulin secretion by pancreatic β-cells and impaired responsiveness of insulin-sensitive tissues." (PMID 38968192, 2024). "Type 2 diabetes mellitus (DM) is a metabolic disorder characterized by persistent hyperglycemia and diminished insulin secretion, leading to disruption in the transfer of glucose from the bloodstream into tissues, which subsequently results in elevated blood glucose concentrations." (PMID 39502985, 2024). "Based on data from the Diabetes Control and Complications Trial (DCCT), intensive insulin therapy seems to prolong the duration of detectable C-peptide levels in people with T1DM." (PMID 39529980, 2024). "However, a significant cost reduction could become evident over an extended time period, as patients with diabetes require more expensive medications such as insulin and are more likely to develop costly complications, which may in turn reduce health‐related quality of life." (PMID 37915263, 2024). "Type 2 diabetes (T2DM), the most common affecting > 90% of people diagnosed with DM, results from an inability of pancreatic β-cells to produce sufficient insulin to stimulate glucose utilization by peripheral metabolically active organs to maintain glucose homoeostasis." (PMID 38966213, 2024). "Type 2 diabetes mellitus (T2DM) is characterized by insulin resistance, impaired insulin secretion, and beta cell dysfunction, leading to chronic hyperglycemia." (PMID 39350820, 2024).
diabetes (continued). "Type 2 diabetes mellitus (T2DM) is a heterogeneous, chronic metabolic disorder categorized by impaired insulin secretion from pancreatic β-cells or by the presence of a persistent hyperglycemic and insulin resistance state." (PMID 39759127, 2024). "Type 2 diabetes mellitus (T2DM) is the most common chronic form of diabetes, with T2DM accounting for more than 90% of all diabetic patients and characterized by resistance to insulin action and an inadequate compensatory insulin secretory response." (PMID 39408825, 2024). "Long-term insulin treatment rescued the majority of the alterations in GLUT protein expression and/or trafficking during diabetes." (PMID 38786744, 2024). "Type 2 diabetes mellitus (T2DM) is characterized by elevated oxidative stress and reduced GSH levels, which detrimentally affect pancreatic β-cell function and insulin sensitivity." (PMID 39857603, 2024). "Postprandial hyperglycemia, commonly referred to as Type 2 Diabetes Mellitus (T2DM), represents a complex metabolic disorder stemming from either dysregulation in insulin sensitivity, insulin secretion, or both." (PMID 39541274, 2024). "Conversely, we had no cases of AP among liver transplanted individuals who were managing their diabetes with SGLT2 inhibitors, metformin, insulin-based therapies or a combination of these molecules (42, 47, 51 and 38 individuals, respectively)." (PMID 38779453, 2024). "Type 2 diabetes mellitus (T2DM) is a chronic metabolic disorder characterized by elevated blood glucose levels owing to inadequate insulin production and insulin resistance." (PMID 39351535, 2024). "Diabetes mellitus (DM) encompasses a range of metabolic diseases characterized by persistent high blood sugar levels, resulting from either the inadequate production of insulin, ineffective insulin action, or both." (PMID 39457658, 2024). "The animal model for diabetes used in this study involves administering STZ via a single injection of i.p., resulting in impaired insulin secretion even at high levels of glycemia and a moderate level of insulin resistance." (PMID 39003280, 2024). "Type 2 diabetes mellitus (T2DM) is a metabolic disorder characterized by chronic hyperglycemia, mostly resulting from impaired insulin production and diminished glucose metabolism regulation." (PMID 39845797, 2024). "Type 1 diabetes mellitus (T1DM) is a chronic disease characterized by autoimmune destruction of pancreatic beta cells, which secrete insulin, a key hormone in glycemic homeostasis." (PMID 39735069, 2024). "Taken together, these data indicate that chronic stimulation of K cell Gs signaling potently counteracted the development of hyperglycemia in a mouse model of diabetes, most likely via GIP-mediated stimulation of insulin secretion." (PMID 39436694, 2024). "Type 2 diabetes mellitus (T2DM) is a chronic metabolic disorder characterized by hyperglycemia resulting from insulin resistance and/or decreased insulin secretion." (PMID 39723311, 2024). "Its capacity to augment insulin release and enhance insulin’s effectiveness in managing hyperglycemia has prompted extensive research into its potential application for diabetes mellitus (DM) treatment." (PMID 38672620, 2024). "Diabetes mellitus (DM) is a group of metabolic diseases with a high prevalence in general population, characterized by hyperglycemia resulting from defects in insulin secretion, insulin action, or both." (PMID 37987916, 2024). "At 7 weeks post-PBMC injection, B2M-/- SC-islets gave rise to positive glucose-stimulated insulin secretion (GSIS) outcomes and were able to reverse diabetes in mice whereas graft function was lost in mice transplanted with WT SC-islets." (PMID 38650946, 2024).